CD68 (CD68 molecule)
Diseases named in the same sentence as CD68 in open-access papers (continued):
Sharing a sentence is not in itself a finding about the gene and the disease.
non-small cell lung carcinoma (22 papers, 2010 to 2025). A group of at least three distinct histological types of lung cancer, including non-small cell squamous cell carcinoma, adenocarcinoma, and large cell carcinoma. "This study demonstrates that the tumor-associated macrophages in non-small cell lung cancer contain two distinct forms, a CD68+/HLA-DR+ M1 form and a CD68+/CD163+ M2 form." (PMID 20338029, 2010). "The findings of this study suggest that both the omega-6/omega-3 ratio and CD68+ macrophage infiltration play important roles in the prognosis of patients with non-small cell lung cancer (NSCLC) undergoing pulmonary resection." (PMID 39330005, 2024). "In both non-small cell lung cancer (NSCLC) and pancreatic adenocarcinoma, VISTA is expressed on CD68+ tumor-associated macrophages." (PMID 36891296, 2023). "Similar findings from the same group have highlighted the improved prognosis which CD68+PD-L1+ cells carry in non-small cell lung cancer when treated with immunotherapy." (PMID 34732817, 2021). "CMTM6 is expressed in advanced non-small-cell lung cancer cells and stromal cells, especially CD68-positive macrophages." (PMID 33818637, 2021). "In contrast, in patients with non-small cell lung cancer (NSCLC), the density of CD68+HLA-DR+ M1-like macrophages in tumor islets is associated with extended survival time." (PMID 34359674, 2021). "In a recent publication, the therapeutic effect of checkpoint inhibitor therapy could even be predicted by observing the levels of CD8/CD68/CD163/PD-L1 positive cells in non-small cell lung cancer." (PMID 36576530, 2023). "Previous studies have identified CD204+ TAMs as prognostic markers in non-small cell lung carcinoma (NSCLC), especially in lung adenocarcinoma, and the combined use of CD47 and CD68 was reported to predict the survival of eastern-Asian patients with NSCLC." (PMID 36077342, 2022). "In addition, a recent study showed that high expression of both CMTM6 and PD-L1, particularly in stromal ICs (CD68 + macrophages) of non-small-cell lung cancer, might identify the patients with the greatest benefit from PD-1 axis blockade." (PMID 33818637, 2021). "Furthermore, scientists were able to localize the expression of the T cell inhibitory molecule VISTA in CD68+ macrophages of human pancreatic cancer and retrieve information on the composition, expansion, and activity of TILs in patients with non-small cell lung cancer (NSCLC)." (PMID 35651929, 2022). "recently found a strong correlation between CD68 TAM immunostaining and PET 18 fluoro-deoxyglucose (FDG) uptake in 98 matched tumors of patients with non-small cell lung cancer (NSCLC)." (PMID 32943999, 2020). "For instance, immune profiling studies on non-small cell lung cancer (NSCLC), renal cancer, and melanoma PDOs with TIME have revealed that the CD8+ and CD4+ T cells, CD14/CD68/CD 69+ macrophages, NK (natural killer), NKT (natural killer T) and B cells were well-maintained in tumor PDO models." (PMID 38256166, 2024). "In addition, HLA-DR+CD68+ M1-like TAM levels significantly decreased during cancer progression, from pathological stage I to III in non-small-cell lung carcinoma (NSCLC)." (PMID 34572013, 2021). "This study confirmed that survival after resection of a non-small cell lung cancer is significantly reduced when the TNM status is improved; in contrast, marked expressions of CD68 and Gas6 as biological markers of the tumour's inflammatory reaction were associated with a favourable outcome." (PMID 21794149, 2011). "Moreover, CD68+ cells are excluded from TLSs, while DC-Lamp+ mature dendritic cells home selectively in TLSs in PDAC, supporting the involvement of TLSs in the promotion of a protective adaptive immunity, as shown in patients with early-stage non-small cell lung cancer." (PMID 34252585, 2021).
osteosarcoma (22 papers, 2016 to 2025). A usually aggressive malignant bone-forming mesenchymal neoplasm, predominantly affecting adolescents and young adults. "High CCL18 levels in serum and osteosarcoma tissues derived from CD68 + M2 TAMs are associated with lung metastases development." (PMID 40442778, 2025). "CD14+/CD68+ tumor-associated macrophages are the predominant immune cells infiltrating osteosarcoma." (PMID 40136652, 2025). "In conclusion, we have shown that tumor infiltration by either CD68+ TAMs or CD1a+ DCs may be associated with poorer survival in osteosarcoma." (PMID 27456063, 2016). "Although previous studies may suggest that the opposite may be the case, we found that the presence of CD68+ TAMs in primary tissue may be significantly associated with worse survival in osteosarcoma." (PMID 27456063, 2016). "In a comparative study involving 20 samples each of Ewing sarcoma and osteosarcoma, the median percentage of CD163+/CD68+ M2‐polarized TAMs was approximately 3% of the tumor area in Ewing sarcoma, notably lower than the ∼15% observed in osteosarcoma." (PMID 41357670, 2025). "CD68 + M2 TAMs detected in untreated osteosarcomas were measurably similar between local and metastatic disease but M1 TAMs were significantly more abundant in non-metastatic than metastatic patients." (PMID 40442778, 2025). "Ten osteosarcoma patient samples were also stained in a multiplex machine for the same markers, and showed a range in expression of both CD68 and CD105 staining." (PMID 39724514, 2024). "The 3D bone model also showed similar characteristics to osteosarcoma patient samples including CD68 and CD105 expression." (PMID 39724514, 2024). "As the aim of the 3D bone model was to replicate aspects of the human osteosarcoma microenvironment, ten osteosarcoma patient samples were sectioned and stained for CD68 and CD105." (PMID 39724514, 2024). "In this case, atypical vimentin-positive spindle cell and CD68-positive giant cell in the sarcoma component are similar to one case of sarcoma and one case of osteosarcoma nodule.Sarcomatoid nodules were sometimes weakly positive for CK." (PMID 38903727, 2024). "In particular, high infiltration of CD68+ TAMs in the dedifferentiated chondrosarcoma with osteosarcoma compartment is correlated with short OS." (PMID 37296922, 2023). "A comprehensive study described that CD14+/CD68+ TAMs represent the main infiltrating immune cell types in bone sarcomas, including osteosarcoma." (PMID 33363016, 2020). "For instance, Han’s group observed that CD68 was significantly higher in osteosarcoma tissues of patients with detectable metastasis than patients without metastasis." (PMID 33363016, 2020). "The only significant density correlation between PD‐L1 and the macrophage marker CD68 was observed in osteosarcoma." (PMID 31922656, 2020). "Infiltrating CD68+ cells were higher in tumor tissues of osteosarcoma patients who were poorly reactive to neoadjuvant chemotherapy." (PMID 33363016, 2020). "CD47-expressing osteosarcoma specimens showed significantly (p < 0.001) higher levels of TAM markers CD68 and CD163 compared to osteomas and normal bones." (PMID 30674867, 2019). "In order to clarify the role of macrophages in osteosarcoma, future studies should correlate the presence of CD68+/CD80+ M1 and CD68+/CD163+ M2 macrophages to osteosarcoma survival." (PMID 27456063, 2016). "For example, a high infiltration of CD68+ TAMs tended to be associated with worse overall survival in the dedifferentiated chondrosarcoma with the osteosarcoma compartment, and the CD68/CD8 ratio was identified as an independent weak prognostic factor of OS in these patients." (PMID 37958467, 2023). "Hence, the infiltration of Th1 CD4 + T cells and CD68 + macrophages in tissues is the key to affecting the efficacy of neoadjuvant chemotherapy and prognosis in osteosarcoma patients." (PMID 32850346, 2020).
osteosarcoma (continued). "In addition, osteosarcoma presented the four cases with highest CD68 density z‐scores observed across all indications, two of these cases having high PD‐L1 and the other two low‐range PD‐L1 density z‐scores." (PMID 31922656, 2020). "It is also possible that osteoclasts, a subset of CD68+ bone specific macrophages, may impact osteosarcoma patient survival." (PMID 27456063, 2016). "Therefore, OCs increase the observed value of the CD68-marker in osteosarcoma." (PMID 33498676, 2021). "Clinical sample results show that the infiltration abundance of CD68 +macrophages and Th1 CD4 + cells was positively correlated with each other and prone to be better prognosis of osteosarcoma and efficacy of neoadjuvant chemotherapy in OSA." (PMID 32850346, 2020). "For instance, Gomez and his colleagues proposed a systematic analysis of CD68, CD163, CD8, PD1 and PDL-1 expression performed in osteosarcoma biopsies to stratify patients regarding their respective TME and suggested a therapeutic strategy targeting macrophages and other immunological factors." (PMID 33363016, 2020). "Although the prognostic relevance of CD68+ and CD163+ macrophage infiltration in osteosarcoma was not described, lower SIRPα levels were associated with a worse overall survival among non-translocation sarcomas, and CD47 expression turned out to be a poor prognostic factor in osteosarcomas." (PMID 33802565, 2021). "On the other hand, osteosarcoma is immunohistochemically negative for pancytokeratins 7 and 20, epithelial membrane antigens, CD34, and CD68." (PMID 35331306, 2022). "In human STS, UPS and Myxofibrosarcomas were found to have the highest median macrophage score of all sarcoma types, and a high number of CD68+ macrophages are discussed as negative prognostic factors for a series of STS, including Osteosarcoma and Ewing Sarcoma." (PMID 36508875, 2023).
viral infection (22 papers, 2013 to 2025). "Lymphoid and natural killer cells decrease with aging, while macrophages, and particularly inflammatory CD68 + macrophages, increase, explaining the age-related deficiency in combatting viral infections and the tendency to easily develop hyper-inflammation." (PMID 35999337, 2022). "Groups of recruited, amoeboid cells showing CD68-immunopositivity indicating phagocytic activity were also observed at sites of virus infection." (PMID 30027450, 2018). "In VACV-treated tumors the 19F-positive hot spots, which showed a similar distribution pattern as the CD68+-macrophage population, encapsulated the viral infection focus and formed a “partial/hollow sphere” localized to the tumor rim." (PMID 23441176, 2013). "One of the observations supporting this hypothesis is the presence of granulomatous inflammation, shown to be mediated by CD68 expressing monocyte/macrophages, and is consistent with a chronic viral infection phenotype." (PMID 28886065, 2017). "Thereby, the CD68+-macrophages encapsulate the GFP-positive viral infection foci." (PMID 23441176, 2013). "The biopsy analysis included polymerase chain reaction diagnosis of viral infection, morphological, immunohistochemical (IHC) examination with antibodies to CD3, CD45, CD68, CD20, SARS‐Cov‐2 spike, and nucleocapsid antigens." (PMID 35855554, 2022). "After virus infection, CD31+ endothelium and CD68+ macrophages remained." (PMID 38627497, 2024). "Interestingly, we also detected in SARS-CoV-2-infected lung tissues, some syncytia that expressed macrophage marker, CD68, NLRP3 and viral RNA, revealing a potential link between NLRP3 expression and viral infection." (PMID 37920468, 2023). "Furthermore, we investigated the correlation between viral infection status (EBER1 and HPV16/18), MIF, and macrophage markers (CD68, CD11c, and CD163) in NPC cases using Spearman’s correlation test." (PMID 34407796, 2021). "In regions with more prolonged viral infection (i.e., the rostral region of the brain), infiltrating Ly6Chi macrophages had lower Ly6C expression and higher expression of CX3CR1, TMEM119, P2RY12, CD64, CD68 and MHC-II, compared to those in the caudal regions." (PMID 34311763, 2021). "The increase in CD8 and cytotoxic T cells, PDL1 and CD68 markers only in EBV+ DLBCL may indicate that traces of viral infection might not have influence in immune response markers." (PMID 38280007, 2024). "In addition, the migration of CD68+ and CD8+ T cells could indicate those cells playing a role in the cytotoxic response in such lesions as a way to contain viral infection, leading to secretion of proinflammatory cytokines and chemokines in the cortical and medullary regions of the kidney." (PMID 31703246, 2019).
lung adenocarcinoma (21 papers, 2016 to 2025). A carcinoma that arises from the lung and is characterized by the presence of malignant glandular epithelial cells. "As shown in this study, the immunohistochemistry results in lung adenocarcinoma tissues revealed that the positive expression of CD68 correlated with a loss of E-cadherin expression and positive expression of LeY." (PMID 28423676, 2017). "The findings of the current study revealed that CD68+ TAM infiltration have prognostic significance in lung adenocarcinoma brain metastases." (PMID 38267913, 2024). "Studies have shown that high expression levels of CD68 are significantly and positively related to the number of neoantigens in lung adenocarcinoma." (PMID 39338178, 2024). "Heterogeneity and Vascular Interactions mIHC and spatial transcriptomic analyses of lung adenocarcinoma tissues have identified several macrophage subtypes, including CD68+, CD68 + D163+, CD68 + CD206+." (PMID 39068459, 2024). "The expression of B7-H4 and the infiltration of CD68+ TAM are independent prognostic factors for lung adenocarcinoma brain metastasis patients." (PMID 38267913, 2024). "Further, CD68+CD163+ or CD68+CD206+ markers were used to identify M2-polarized TAMs in lung adenocarcinoma." (PMID 36077342, 2022). "In our previous report, tumor samples from patients with lung adenocarcinoma showed MAFB expression in locations comparable to CD68- and CD204-positive TAMs and were abundant in severe stages of cancer." (PMID 36077342, 2022). "To investigate if reduced CD68+/CD163+ TAMs within in situ regions has an impact on lung adenocarcinoma development, we first assessed the link between statin use and pathological tumor staging." (PMID 32190817, 2020). "Here we determined the expression of CD68 and E-Cadherin in 60 lung adenocarcinoma tissues using immunohistochemistry." (PMID 28423676, 2017). "Cells within the magnetic fraction were strongly CD68 positive demonstrating that TAMs accumulate iron in lung adenocarcinoma." (PMID 29167669, 2017). "B7-H4 and CD68+ TAMs may have potential therapeutic value for lung adenocarcinoma brain metastases patients." (PMID 38267913, 2024). "Hence, we predicted that during radiotherapy, alterations of the percentages of MDSCs are more sensitive in lung adenocarcinoma patients, while CD68+CD163+M2-like macrophages are more specific for lung squamous carcinoma patients." (PMID 35928634, 2022). "A previous report proposed that CD204 could be a better marker than CD68, a pan-macrophage/monocyte marker, for the identification of tumor-promoting TAMs in patients with lung adenocarcinoma." (PMID 29850577, 2018). "Furthermore, we revealed an increase in the numbers of infiltrating CD68+ macrophages in the alveolar septum surrounding the lung adenocarcinoma." (PMID 28801561, 2017). "We validated our findings in surgically resected specimens from 20 primary lung adenocarcinoma patients by immunofluorescence staining and revealed a positive correlation between frequencies of CDKN2A+ senescent cells and CD73+CD68+ macrophages." (PMID 38323313, 2024). "The expression of TNF-α, IL-6, and macrophage marker CD68, as well as E-cadherin, vimentin, Twist, matrix metalloproteinase (MMP)-2, MMP-9, and SOD-2 were examined in AFG1-induced lung adenocarcinoma." (PMID 28801561, 2017). "For example, in lung adenocarcinoma in mice, it was demonstrated that the bacteria Diaphorobacter nitroreducens, when combined with oxaliplatin, increased the number of CD163- and CD68-positive macrophages while reducing Treg cells (CD4 FOXP3), thus slowing tumor progression." (PMID 40075568, 2025). "In addition, we also explored the factors related to the prognosis of patients with lung adenocarcinoma brain metastases, and the results revealed the age, expression of B7-H4 and IDO1, and infiltration of CD68+ TAM were related to the prognosis." (PMID 38267913, 2024).
lung adenocarcinoma (continued). "We also investigated whether there was a correlation between SPP1 gene expression and various macrophage markers, such as CD204, Iba-1, CD68, CD163, and CD163L1, in lung adenocarcinoma tissues." (PMID 36139536, 2022). "Pearson correlation analyses of TGCA data showed that AIF-1 expression was significantly positively correlated with CD68 expression (a macrophage marker) in NSCLC (r = 0.600, P < 0.001), lung SCC (r = 0.590, P < 0.001) and lung adenocarcinoma (r = 0.600, P < 0.001)." (PMID 36520870, 2022). "Immunohistochemical analysis showed positive staining for CK (AE1/AE3), TTF-1, and p40, while CK56, CD68, CD45 (LCA), D2-40, and Ki-67 (50%+) were negative, leading to the diagnosis of lung adenocarcinoma." (PMID 39928773, 2025). "We next investigated whether there was an association between statin use and TAM number and polarity by quantitation of CD68/CD163 staining in statin users and nonusers among the 262 lung adenocarcinoma cohort." (PMID 32190817, 2020).